APOE (apolipoprotein E)
Diseases named in the same sentence as APOE in open-access papers (continued):
Sharing a sentence is not in itself a finding about the gene and the disease.
atherosclerosis (continued). "Thus, the apoE-/- mouse model offers an opportunity to examine and understand the interaction of vascular endothelial dysfunction and senescence that is associated with the pathogenesis of atherosclerosis." (PMID 22082357, 2011). "The fact that tissue arginase was elevated only in apoE−/− mice on the HC diet raises the possibility that the mechanism(s) underlying increased arginase expression also may be part of the inflammatory process leading to atherosclerosis." (PMID 21151916, 2010). "This could lead to a reduced apoE protective effect, during the development of adipose tissue and, in particular, during inflammation, thus potentially leading to an increased risk of developing atherosclerosis." (PMID 20642861, 2010). "In an ApoE-/- mouse model of atherosclerosis, this integrated platform effectively cleared plaque senescent cells, attenuated disease progression, and showed a favorable safety profile." (PMID 42159453, 2026). "ApoE−/− mice were fed a Western diet for 4 weeks to establish an atherosclerosis model for further experiments." (PMID 41035425, 2026). "CTRP4 deficiency promotes the development of atherosclerosis in ApoE‒/‒ mice, whereas CTRP4 supplementation attenuates atherosclerosis via binding and inhibition of RAGE and TLR4." (PMID 41705294, 2026). "Next, an atherosclerosis model was established in ApoE-/- mice fed a high-fat diet for 16 weeks, and the therapeutic effects of JZRM were evaluated based on serum lipids, glucose, bile acids, and aortic plaque area." (PMID 42291552, 2026). "We aimed to evaluate the efficacy of diacerein, an IL-1 pathway inhibitor, in improving liver fibrosis, steatosis, and atherosclerosis in apolipoprotein E-knockout (apoE k/o) mice." (PMID 41811513, 2026). "Diacerein treatment ameliorated liver steatosis/fibrosis and showed beneficial effects on atherosclerosis-related mechanisms in HFD-fed apoE k/o mice." (PMID 41811513, 2026). "Collectively, these results demonstrate that endothelial-specific METTL14-N overexpression attenuates atherosclerosis progression in ApoE−/− mice, highlighting its potential as a protein-based therapeutic strategy for treating atherosclerosis." (PMID 41510160, 2026). "Here, we examined the role of muFHR1 in perpetuating atherosclerosis in muFHR1-/-ApoE-/- double knockout (KO) mice and ApoE-/- mice expressing muFHR1." (PMID 41583528, 2026). "This study aimed to investigate the efficacy of purslane extract in ameliorating atherosclerosis in apolipoprotein E(ApoE) knock-out (ApoE-/-) mice." (PMID 41896950, 2026). "KEY MESSAGES: We analyzed the effects of diacerein on liver fibrosis, steatosis, and atherosclerosis in apolipoprotein E knockout (apoE k/o) mice." (PMID 41811513, 2026). "To gain a broader understanding of ICP axes during atherosclerosis, we analyzed transcriptomic data from aortas of atherogenic ApoE−/− and wild-type (WT) mice fed with either a normal diet (ND) or high-fat diet (HFD) at early and late stages of disease." (PMID 41216502, 2026). "Genetic galectin-3 deficiency attenuated, and conversely nigericin exacerbated macrophage death, vascular inflammation and atherosclerosis in HFD-fed ApoE-/- mice." (PMID 41795807, 2026). "Recently, we have reported that specific blocking of MC signaling with esaxerenone shows beneficial effects on the development of atherosclerosis in STZ-induced diabetic ApoE KO mice." (PMID 41585322, 2026). "This study aims to investigate the effects of PSB on suppressing atherosclerosis in vivo and to explore the underlying mechanisms.A high-fat diet was used to induce the development of atherosclerosis in ApoE-/- mice for 12 weeks." (PMID 42085490, 2026).
atherosclerosis (continued). "We also showed that dh404 reduces inflammation and atherosclerosis in diabetic apolipoprotein E knockout (Apo−/−) mice." (PMID 41300435, 2025). "To study the effect of ANRIL on atherosclerosis in TgANRIL mice in vivo, we crossed TgANRIL mice with ApoE−/− mice to develop ApoE−/−ANRIL mice and assessed aortic atherosclerosis after feeding with a Western diet for 14 weeks." (PMID 40383150, 2025). "To test this concept in ApoE−/− mice, one of the most widely used animal models for dyslipidemia-induced atherosclerosis research, we employed an implantable osmotic pump (ALZET model 2006)." (PMID 40003949, 2025). "To investigate the effect of macrophage-specific ORP2 overexpression on hyperlipidemia and atherosclerosis, we crossed hORP2MOE mice with ApoE−/− mice, which are prone to hypercholesterolemia and atherosclerosis, to generate hORP2MOE/ApoE−/− mice." (PMID 40349776, 2025). "Bicyclol improves high-fat diet-induced atherosclerosis in ApoE-/- mice by restoring gut health and alleviating endothelial activation, macrophage infiltration, and cholesterol ester accumulation." (PMID 40356907, 2025). "Additional validation in models mimicking atherosclerosis-related thrombosis (e.g., ApoE−/− mice or high-fat diet-induced models) would further enhance the translational relevance of this study." (PMID 41462935, 2025). "In this study, based on the atherosclerosis apoE−/− mice model induced by an HFD, we further verified the effect of CGE on the PPAR-γ-LXR-α-ABCA1 signaling pathway." (PMID 41464973, 2025). "A diabetic atherosclerosis mouse model was implemented by combining ApoE−/− mice with a streptozocin STZ-induced diabetic phenotype." (PMID 40421131, 2025). "Together, our data show direct and indirect effects of platelet Jak2 in mediating systemic inflammatory response that likely led to accelerated atherosclerosis in ApoE−/−P-Jak2 KO mice." (PMID 40825505, 2025). "For example, multiple studies demonstrate that Mitochondrial Division Inhibitor 1 (Mdivi-1), which reversibly inhibits Complex I of the ETC to modify mtROS production, reduces atherosclerosis in ApoE−/− mice." (PMID 41300435, 2025). "To elucidate the exact role of IGFBP5 in atherosclerosis, we overexpressed IGFBP5 in the classic atherosclerosis mouse model, ApoE−/− mice." (PMID 40729024, 2025). "Animal studies confirmed that NP exposures activated phagocytosis of macrophage and also promoted VSMC migration, likely contributing to increased atherosclerosis in ApoE-/- mice." (PMID 40857741, 2025). "The depletion of CD8+ T cells using antibodies in high-fat fed ApoE-/- mice has been shown by several studies to attenuate atherosclerosis." (PMID 40510365, 2025). "Different APOE isoforms have varying effects on LDL-C concentrations and atherosclerosis risk, significantly impacting cardiovascular health." (PMID 40362720, 2025). "The atherosclerosis model was established using ApoE-/- mice fed with a “Western diet” followed by treatment with NGR1, SSB2, or NS combination." (PMID 40577270, 2025). "Our study demonstrates the effect of blocking opioid receptors with naloxone (NLX) on cholesterol levels and atherosclerotic plaque formation in ApoE−/− mice with advanced atherosclerosis." (PMID 40868056, 2025). "In this study, BPQDs were first applied to the treatment of atherosclerosis in high fat diet ApoE-/- model mice that BPQDs were given every other day for 3 weeks without changing the high-fat diet." (PMID 39998897, 2025).
atherosclerosis (continued). "Another study performed on PGRN-ApoE double-knockout mice found that the lack of PGRN in the context of a high-fat diet contributed to more severe atherosclerosis compared to that of mice with the ApoE knockout alone." (PMID 41155225, 2025). "The ApoE–/– murine model of atherosclerosis is advantageous due to its representation of inflammation yet has several limitations in recapitulation of human lipid metabolism." (PMID 40779455, 2025). "We used male ApoE−/− C57BL/6 mice to induce atherosclerosis by feeding a high-fat diet in this study." (PMID 40636499, 2025). "In a recent review, it has been discussed how different isoforms of ApoE, in particular the ApoE4, can affect the progression of atherosclerosis in patients with periodontal disease." (PMID 40406630, 2025). "In this study, black phosphorus quantum dots (BPQDs) were applied to the treatment of atherosclerosis in high fat diet ApoE-/- model mice that BPQDs were given every other day for 3 weeks without changing the high-fat diet." (PMID 39998897, 2025). "ApoE knockout mice were fed with a high cholesterol diet to establish a mouse atherosclerosis model." (PMID 40266108, 2025). "Development of atherosclerosis in the aortas of ApoE−/− mice was pre-demonstrated by Oil Red O staining." (PMID 40630903, 2025). "In an apolipoprotein E–knockout (ApoE)–/– mouse model of atherosclerosis, SerBut reduced systemic LDL-C, proinflammatory cytokines, and circulating neutrophils." (PMID 40779455, 2025). "Compared with the HFD group (15 weeks of HFD feeding), the HFD+PEMFs group exhibited significantly slower the progression of atherosclerosis in ApoE-/- mice." (PMID 41309549, 2025). "Peanut Skin Extract significantly mitigates atherosclerosis in ApoE-/- mice by regulating lipid metabolism, exerting anti-inflammatory effects, and altering gut microbiota composition." (PMID 40356907, 2025). "The vaccination with the ApoB-100 peptide P210 also reduced the development of atherosclerosis in ApoE −/− mice." (PMID 40823653, 2025). "In this study, we selected ApoE−/− mice as the main research subjects, as they are the most commonly used animal model of spontaneous atherosclerosis and exhibit a significant increase in plasma cholesterol." (PMID 40729024, 2025). "The physiological changes in FS and EF in the ApoE-KO mouse model are analogous to the cardiac functional decline seen in human patients with advanced atherosclerosis and heart failure." (PMID 41194853, 2025). "Many studies use APOE-knockout murine models to study accelerated atherosclerosis and effects of estrogen, underscoring the importance of this ligand in atherosclerotic pathology." (PMID 40182431, 2025). "Given that Jak2 is a major inflammatory mediator, we investigated the essential endogenous role of platelet Jak2 in ApoE−/− model of atherosclerosis." (PMID 40825505, 2025). "By performing partial carotid ligation in ApoE−/− and ApoE−/−/ALOX15−/− mice, we showed that atherosclerosis under disturbed flow was attenuated by 12/15-LOX deficiency." (PMID 40660143, 2025). "The finding that the germline AnxA8 deficiency drastically reduces the atherosclerotic burden in both early and advanced atherosclerosis in an ApoE−/− mouse model argues for a functional role of AnxA8 in the progression of atherosclerosis." (PMID 39835780, 2025). "Cyclodextrins modulate the production of oxysterols by macrophages, promote LXR-mediated cholesterol efflux, and contribute to the regression of atherosclerosis in ApoE−/− mice." (PMID 39936975, 2025). "A prior Pla2g15−/− knockout study also reported its presence in foam cells within atherosclerotic lesions in apoE−/− mice, suggesting a role in atherosclerosis." (PMID 40689090, 2025). "To assess the pathological roles of AEP in atherosclerosis development in the aorta in APOE–/– mice, we crossed APOE–/– mice with AEP–/– mice and subsequently fed WT mice and single- and double-KO mice with a HFD consecutively for 12 weeks." (PMID 40371638, 2025).
atherosclerosis (continued). "Low apoE levels observed in individuals with atherosclerosis further suggest a potential mechanistic connection." (PMID 40275327, 2025). "In this study, ApoE (−/−) mouse model is widely used in atherosclerosis research due to its ability to spontaneously develop hyperlipidemia and atherosclerotic lesions resembling human pathology." (PMID 40598260, 2025). "The flavonoid fisetin was studied for its impact on atherosclerosis in mice with an apoE−/− genotype." (PMID 41470139, 2025). "In our study, we aimed to evaluate the efficacy of oral administration of T-K in alleviating atherosclerosis in ApoE knockout (ApoE−/−) mice." (PMID 41244676, 2025). "While expression of Mfn2 has increased in wild-type macrophages as well as brain and cardiac cells, in ApoE-/- mice, the expression of Mfn2 was significantly reduced during atherosclerosis progression." (PMID 39940788, 2025). "APOE KO mice have frequently been used as a model for atherosclerosis, giving rise to foamy cells laden with cholesterol crystals." (PMID 41196656, 2025). "AEP is activated in the liver and aorta of apolipoprotein E–null (APOE-null) mice, and deletion of AEP from APOE–/– mice attenuates atherosclerosis." (PMID 40371638, 2025). "APOE has anti-inflammatory roles in modulating macrophage behavior and regulating neutrophils, as observed in atherosclerosis." (PMID 40962953, 2025). "Irradiation has been reported to accelerate the development of atherosclerosis in the carotid artery and the aorta of ApoE–/– mice." (PMID 40044924, 2025). "In apolipoprotein E (ApoE)−/− atherosclerosis models, 8-week oral F1 treatment at 50 mg/kg/day induced remarkable reduction in atherosclerotic lesion area and decreased lectin-like oxidized low-density lipoprotein receptor-1 (LOX-1) and TLR4 expression." (PMID 41155644, 2025). "In this study, we aimed to investigate the effectiveness of an approach designed to overexpress IL‐10 in macrophages and subsequently introduce these genetically modified cells into ApoE−/− mice to promote atherosclerosis regression." (PMID 39801756, 2025). "We further analyzed pathological lesions in the liver tissue sections of ApoE−/− mice and evaluated the severity of atherosclerosis based on H&E staining of the paraffin-embedded sections." (PMID 40407263, 2025). "TLR9 activation decreases the severity of atherosclerosis in ApoE−/− mice fed with a high-fat diet (HFD)." (PMID 40076851, 2025). "Whilst various genetically modified strains, such as atherosclerosis-prone, apolipoprotein-E (ApoE) knockouts are available for use, current literature typically use wild-type of genetically healthy species of animals." (PMID 41268343, 2025). "Nampt-specific knockdown can promote reverse cholesterol transport and attenuate atherosclerosis in Apolipoprotein E knockout (ApoE−/−) mice." (PMID 40143060, 2025). "Our results show that addressing these challenges significantly accentuates the benefit of butyrate dosing in the ApoE–/– model of atherosclerosis compared with treatment with NaBut." (PMID 40779455, 2025). "Unlike before, NMN1 (300 mg/kg) was given intragastrically and daily for 2 months after 2 months of HFD-induced atherosclerosis formation in ApoE−/− mice (4 months of HFD and 2 months of NMN1 intragastrically)." (PMID 40143060, 2025). "Mice with knockout of apolipoprotein E and scavenger receptor class B type I genes used to model atherosclerosis are characterized by frequent undesirable complications in the form of spontaneous plaque ruptures with subsequent infarction in target organs." (PMID 40722594, 2025). "The atherosclerotic lesions in ApoE−/− mice are similar to the developmental and pathological processes of atherosclerosis in humans." (PMID 40636499, 2025).
atherosclerosis (continued). "To ascertain the pathological roles of AEP in atherosclerosis, we fed 2-month-old APOE–/– mice with a HFD mixed with #11a (7.5 mg/kg) or statin (10.0 mg/kg) for 12 weeks." (PMID 40371638, 2025). "The transfer of B cells from older atherosclerotic ApoE−/− mice had a beneficial effect on the progression of atherosclerosis in mice that had undergone splenectomy." (PMID 40823653, 2025). "In apoE-deficient or LDL-receptor-deficient mice, RAGE deletion significantly reduced the extent of atherosclerosis and vascular inflammation compared to wild-type controls, irrespective of diabetic status." (PMID 40806443, 2025). "Perinatal exposure to BPA led to atherosclerosis in adult male PXR-humanized mice and PXR-humanized ApoE-deficient mice." (PMID 40726484, 2025). "Multiple studies demonstrate that anti-CD40L antibodies or CD154 knockout (KO) effectively suppress inflammatory responses and inhibit atherosclerosis progression in ApoE-/- mice." (PMID 41268556, 2025). "ApoE, known for its protective role in clearing lipoproteins from circulation and preventing atherosclerosis, was significantly increased in the aortic arch of MerTKflox/flox mice but markedly reduced in MerTKflox/floxTie2Cre mice." (PMID 40953531, 2025). "We found that EC-specific 12/15-LOX knockdown markedly reduced atherosclerosis in ApoE−/− mice after carotid artery partial ligation." (PMID 40660143, 2025). "ApoE−/− mice fed with a high-fat diet (HFD) for 18 weeks were used to establish atherosclerosis model." (PMID 40407263, 2025). "The IPA database encompassed 16 projects, including ApoE−/− versus WT, atherosclerosis versus normal control in young and aged populations, and high-fat diet versus chow diet in WT mice." (PMID 40953531, 2025). "CELSR2, FN1, SPARCL1, APOE, LPA, APOA5, and TGFB1 exhibit causal associations with both atherosclerosis and four cardiovascular diseases, suggesting their potential as therapeutic targets for atherosclerosis." (PMID 40649979, 2025). "We established an atherosclerosis model using ApoE−/− mice, with C57BL/6 wild‐type mice serving as the control group." (PMID 40548932, 2025). "Using smooth muscle-specific Senp3 knockout mice on an ApoE−/− background, we demonstrated that Senp3 deletion attenuates atherosclerosis, promotes plaque stability, and preserves the contractile VSMCs phenotype." (PMID 41307849, 2025). "ApoE knockout (KO) mice, a standard model of atherosclerosis, exhibited increased miR-155 expression in the mice aorta after 3 weeks on HFD and 6 hours of lipopolysaccharide (LPS) stimulation." (PMID 40565538, 2025). "Both co- and posttreatment of KMUP-1 stimulated autophagy and reduced inflammation and apoptosis, against atherosclerosis and cardiac remodeling in an ApoE-KO mouse model." (PMID 41194853, 2025). "In the present study, we used an apolipoprotein E knockout (ApoE−/−) mouse model to address the effect of sodium nitrate on senescence accompanied by atherosclerosis." (PMID 40110129, 2025). "In this study, atherosclerosis and cardiac damage were induced in ApoE knockout (KO) mice by feeding them a high-fat diet (HFD) for 12 weeks." (PMID 41194853, 2025). "Tan IIA has been shown to modulate this process through its ability to alleviate atherosclerosis in ApoE−/− mice by orchestrating the crosstalk between autophagy and macrophage polarization via KLF4 activation and miR-375 suppression." (PMID 40689206, 2025).